ANXA2 (annexin A2)
Diseases named in the same sentence as ANXA2 in open-access papers (continued):
Sharing a sentence is not in itself a finding about the gene and the disease.
coronary artery calcification (1 paper, 2020). Calcification of the coronary artery, used as a measure of coronary atherosclerosis, a risk factor for myocardial infarction. "Furthermore, the levels of both Fetuin-A and MGP in plasma exosomes were negatively while the levels of Annexin-A2 in plasma exosomes was positively correlated to coronary artery calcification scores (CACS)." (PMID 33585452, 2020).
Crohn disease (1 paper, 2020). A gastrointestinal disorder characterized by chronic inflammation involving all layers of the intestinal wall, noncaseating granulomas affecting the intestinal wall and regional lymph nodes, and transmural fibrosis. "As observed in the salmon intestine, the mRNA levels of Annexin A2 were higher in the inflamed mucosa of patients with Crohn’s disease." (PMID 33362778, 2020).
cryptococcal infections (1 paper, 2024). "In studies on cryptococcal infections, the macrophages in ANXA2-deficient mice were found to phagocytose yeast cells less efficiently than those in mice with a normal expression of ANXA2." (PMID 39057791, 2024).
Desminopathy (1 paper, 2024). "The common hub genes in desminopathy and titinopathy were cytoskeleton- (ACTB, ANXA2), and ECM-related (CD44)." (PMID 39239540, 2024).
disc degeneration (1 paper, 2024). "In summary, hypoxia‐induced BMSC exosomes deliver BNIP3‐rich vesicles to alleviate disc degeneration by activating the mitochondrial BNIP3/ANXA2/TFEB axis, providing a new target for IVDD treatment." (PMID 38973294, 2024).
Dysmenorrhea (1 paper, 2019). Pain during menstruation that interferes with daily activities. "It is suggested that ANXA2 is involved in the occurrence of AM and dysmenorrhea, and promotes the development of AM and the aggravation of dysmenorrhea." (PMID 31183557, 2019). "Gene-targeting therapy for ANXA2, a biological target, provides a new therapeutic approach to alleviate dysmenorrhea in AM patients and to meet the conservative and fertility requirements of some patients after the open second-child policy." (PMID 31183557, 2019). "The expression level of ANXA2 in AM ectopic endometrium was positively correlated with dysmenorrhea degree (R = 0.831, P = 0.000)." (PMID 31183557, 2019). "The relationship between ANXA2 expression and dysmenorrhea in AM tissues was tested in this study." (PMID 31183557, 2019).
E. coli infections (1 paper, 2017). "It is well established that annexin A2 (ANXA2) plays a critical role as a host mediator of bacterial pathogens and is essential in the pathogenesis of Enteropathogenic E. coli infections." (PMID 28848713, 2017).
edema (1 paper, 2020). An abnormal accumulation of fluid beneath the skin, or in one or more cavities of the body. "Anxa2-/-, but not Anxa2+/+, mice also displayed an acute inflammatory response with infiltration of neutrophils into the lung parenchyma and development of pulmonary edema." (PMID 32575495, 2020).
endometrial tumor (1 paper, 2019). "We then analyzed the protein levels of L1CAM and ANXA2 by ELISA in the purified EVs, known biomarkers with prognostic value in endometrial tumor tissue samples." (PMID 31842290, 2019).
endometrioid tumor (1 paper, 2019). A benign, borderline, or malignant epithelial tumor of the female reproductive system characterized by the presence of glands and/or cysts lined by neoplastic cells that resemble endometrial cells. "Moreover, we could observe high ANXA2 levels in plasmatic EVs associated with non-endometrioid tumors and high risk of recurrence tumors, evidencing the potential use of EV-based ANXA2 expression as a diagnostic and prognostic liquid biopsy biomarker in EC." (PMID 31842290, 2019).
endothelial dysfunction (1 paper, 2025). In vascular diseases, endothelial dysfunction is a systemic pathological state of the endothelium (the inner lining of blood vessels) and can be broadly defined as an imbalance between vasodilating and vasoconstricting substances produced by (or acting on) the endothelium. "The most common findings include endothelial dysfunction with thrombosis, chorangiosis, villous edema, and fibrinoid necrosis, as well as the increased expression of sclerostin and Annexin A2." (PMID 40943516, 2025).
endotoxemia (1 paper, 2015). "In summary, our results have demonstrated that AnxA2 molecules interact with a TRAM-TRIF adaptor complex and subsequently regulate TLR4 endosomal signaling and its anti-inflammatory action during endotoxemia." (PMID 26527544, 2015).
fibromatosis (1 paper, 2021). A poorly circumscribed neoplasm arising from the soft tissues. "ANXA2 and ANXA5 were both under-expressed in the mutant GFs; we anticipate that dysregulated responses of ERS GFs to chronic inflammatory and fibrotic conditions may contribute to the fibromatosis." (PMID 34777248, 2021).
glaucoma (1 paper, 2023). Increased pressure in the eyeball due to obstruction of the outflow of aqueous humor. "In addition, ANXA2 has been shown to act synergistically with its ligand tPA in Pten deletion–induced axon regeneration disease, significantly protecting RGC stomata and preserving visual function in a glaucoma model." (PMID 37828081, 2023).
glomerulosclerosis (1 paper, 2023). A hardening of the kidney glomerulus caused by scarring of the blood vessels. "Latest reports have demonstrated that there is a link of annexin A2 involvement during glomerulosclerosis by which collagen type VI is secreted via renal glomerular endothelial cells." (PMID 37627907, 2023).
gram-negative bacterial infections (1 paper, 2016). Infections caused by bacteria that show up as pink (negative) when treated by the gram-staining method. "Previously, we have found that AnxA2 is involved in Gram-negative bacterial infection." (PMID 27389701, 2016).
hepatitis B virus infection (1 paper, 2014). A viral infection caused by the hepatitis B virus. "ANXA2 levels have been found to correlate with hepatitis B virus infection, extrahepatic metastasis and portal vein thrombus." (PMID 24348815, 2014).
hepatitis C (1 paper, 2022). "In the KEGG pathway analysis, the upregulated genes in the ANXA2 knockdown cells were mainly associated with inflammatory pathways, including influenza A, herpes simplex infection, measles, RIG-I-like receptor signaling pathway, hepatitis C." (PMID 35906541, 2022).
herpesvirus infection (1 paper, 2013). "The role of Annexin A2 in herpesvirus infection has mainly been studied with HCMV." (PMID 24386290, 2013).
hydatid disease (1 paper, 2023). "In a study on rats with echinococcosis, treatment with albendazole alone or in combination with matrine alkaloids effectively inhibited echinococcal infection and increased Annexin A2 levels." (PMID 37482693, 2023). "As Annexin A2 is a calcium-binding protein and its levels rise during treatment of echinococcosis, it has been speculated whether Annexin A2 promotes calcification during echinococcosis death." (PMID 37482693, 2023). "Therefore, the increased level of Annexin A2 may be a defence mechanism against hydatid disease." (PMID 37482693, 2023).
invasive ductal carcinoma (1 paper, 2015). "In our previous study, we showed that elevated expression of Anxa2 mRNA correlates with lymph node metastasis of invasive ductal carcinoma (IDC)." (PMID 26307676, 2015).
keloid (1 paper, 2018). An irregularly shaped, elevated mark on the skin caused by deposits of excessive amounts of collagen during wound healing. "The overexpression of annexin A2 has been linked to a variety of tumors and keloid." (PMID 30341243, 2018). "Annexin A2 may participate in keloid formation by inhibiting keloid fibroblast proliferation and may be a valuable therapeutic target for keloid lesions." (PMID 30341243, 2018).
Klebsiella pneumonia (1 paper, 2020). An pneumonia caused by infection with Klebsiella. "In a model of Klebsiella pneumonia in mice, AnxA2 appeared to reduce infection-associated inflammation." (PMID 32575495, 2020). "In Anxa2-/- mice infected intranasally with Klebsiella pneumonia, the level of pro-inflammatory cytokines was significantly elevated, and Anxa2-/- mice exhibited 100% mortality, versus 100% survival for Anxa2+/+ mice at 50 h post injection." (PMID 32575495, 2020).
leishmaniasis (1 paper, 2024). Infectious disease that is transmitted through the bite of hematophagous female phlebotomine sand flies. "ANXA2 and IRAK3 were closely related to the glycine, serine, and threonine metabolism, glyoxylate and dicarboxylate metabolism, Leishmaniasis, propanoate metabolism, valine, leucine, and isoleucine degradation." (PMID 38277535, 2024).
lipid metabolism disorders (1 paper, 2024). "The lipoacyl-binding domain of DBT interacts with annexin A2, activating Hippo signaling, inhibiting tumor progression, and correcting lipid metabolism disorders." (PMID 39315155, 2024).
Lymphatic Metastasis (1 paper, 2014). Transfer of a neoplasm from its primary site to lymph nodes or to distant parts of the body by way of the lymphatic system. "The positive rate of ANXA2 in the lymphatic metastasis group was higher than that that of the non-lymphatic metastasis group (P = 0.03)." (PMID 25362534, 2014).
lymphoma (1 paper, 2017). A malignant (clonal) proliferation of B- lymphocytes or T- lymphocytes which involves the lymph nodes, bone marrow and/or extranodal sites. "Our study added a new evidence about the role of Annexin A2 in transformation of lymphoma." (PMID 28404907, 2017).
meningioma (1 paper, 2020). A generally slow growing tumor attached to the dura mater. "This enabled validation of peptides of several candidate biomarkers like VIM, ANXA2, AHNAK, TS101, and CLIC1 from the surgically resected meningioma tissues and control arachnoid regions." (PMID 32974197, 2020).
mesothelioma (1 paper, 2023). A usually malignant and aggressive neoplasm of the mesothelium which is often associated with exposure to asbestos. "Based on the Cox proportional hazards model, the ANXA2 expression level were related to OS of BLCA (p = .013), CESC (p = .014), HNSC (p = .007), LGG (p < .001), LIHC (p = .021), LUAD (p < .001), mesothelioma (MESO) (p < .001), OV (p = .008), PAAD (p < .001) and uveal melanoma (UVM) (p = .004)." (PMID 36713082, 2023).
myocardial infarction (1 paper, 2024). Gross necrosis of the myocardium, as a result of interruption of the blood supply to the area, as in coronary thrombosis. "For example, the potential SOST target, ANXA2, plays a role in protective vascularization following myocardial infarction, interacting with macrophage YAP and integrin signaling as well as PI3K/AKT signaling." (PMID 39430425, 2024).
ovarian serous tumor (1 paper, 2019). A benign, borderline, or malignant epithelial tumor of the ovary characterized by the presence of neoplastic epithelial cells that, in well differentiated tumors, resemble the epithelial cells of the fallopian tube and, in poorly differentiated tumors, show anaplastic features. "Prognostic analysis suggested that significant correlations occurred between ANXA2/4/8/9 mRNA upregulation and poor overall survival, and between ANXA8/9/11 mRNA upregulation and poor progression-free survival in patients with ovarian serous tumors." (PMID 31474227, 2019). "Upregulation of ANXA2, ANXA4, ANXA8, and ANXA9 mRNAs displayed significant correlations with poor OS in patients with ovarian serous tumors." (PMID 31474227, 2019). "Prognostic analysis suggested that ANXA2 and ANXA4 mRNA upregulation was significantly correlated with poor OS in patients with ovarian serous tumors." (PMID 31474227, 2019).
pancreatitis (1 paper, 2021). Inflammation of the pancreas. "Pancreatitis: In an in vitro rat model of caerulein-induced inflammation of the pancreas, pancreatitis, ANXA2 and FENDRR were found to be increased in pancreatic acinar cells." (PMID 33513839, 2021).
paraganglioma (1 paper, 2023). A benign or malignant neoplasm arising from paraganglia located along the sympathetic or parasympathetic nerves. "ANXA2 expression was positively correlated with the immune cells mentioned before in pheochromocytoma and paraganglioma (PCPG) and PRAD (all r > .3, all p < .05)." (PMID 36713082, 2023).
parasitic infections (1 paper, 2025). "Annexin A2 (ANXA2) is a multifunctional protein involved in host-pathogen interactions during viral and parasitic infections." (PMID 40777830, 2025).
periodontitis (1 paper, 2025). An acute or chronic inflammatory process that affects the tissues that surround and support the teeth. "In conclusion, our data on the secretion of ECV in the inflammatory microenvironment of periodontitis points to AnxA2 as a critical regulator of ECV transport." (PMID 40346842, 2025). "Collectively, these findings indicate a potential role for AnxA2 and vimentin in the amplification of the inflammatory response in periodontitis." (PMID 40346842, 2025). "Targeting the AnxA2‐dependent secretion pathway of ECV may provide a novel strategy to mitigate inflammation‐driven tissue damage in periodontitis." (PMID 40346842, 2025). "The production of extracellular vimentin (ECV) by hGFs in response to periodontitis is mediated by an AnxA2‐dependent unconventional secretory pathway that may play a role in the amplification of the inflammatory response." (PMID 40346842, 2025). "While previous data showed that serum levels of AnxA2 are higher in patients with periodontitis than in healthy controls, the role of AnxA2 in the pathogenesis of periodontitis is not defined." (PMID 40346842, 2025).
peripheral nerve injury (1 paper, 2017). Injury to a peripheral nerve. "Previous studies has revealed that Annexin A2 regulates TRPA1-dependent nociception and may have an important role in neuropathic pain after peripheral nerve injury." (PMID 28928629, 2017).
pharyngeal carcinomas (1 paper, 2022). "In particular, we may anticipate that ANXA2 blocking strategies might be adequate in NPC and OSCC to specifically target its oncopromoter role, but not in other HNSCC subtypes, such as laryngeal and pharyngeal carcinomas, where ANXA2 expression is downregulated and oncosuppressive." (PMID 36247003, 2022).
pharyngeal squamous cell carcinoma (1 paper, 2022). A squamous cell carcinoma that arises from the pharynx. "ANXA2 is upregulated in several tumor subtypes but in HNSCC is usually found downregulated, and low ANXA2 levels associated with poorly differentiated tumors and metastasis in OSCC, laryngeal/pharyngeal squamous cell carcinoma." (PMID 36247003, 2022).
pituitary adenomas (1 paper, 2023). "Further analysis of the molecular mechanisms of ANXA2 in the tumorigenesis and invasion of pituitary adenoma is thus needed." (PMID 36750863, 2023). "The expression levels of ANXA2, PMAIP1, SPRY2, C2CD4A, APOD, FGF14 and FKBP10 were significantly upregulated while FNDC5 and MAP3K4 were downregulated in the invasive gonadotrophic pituitary adenomas compared to the non-invasive ones." (PMID 36750863, 2023).
primary biliary cirrhosis (1 paper, 2020). "ANXA2 is another potentially relevant gene that was significantly upregulated in cholangiocytes in primary biliary cirrhosis from a recent study." (PMID 32848883, 2020).
pulmonary oedema (1 paper, 2021). "Additionally, the role of AnxA2 in maintaining the endothelial cell junctions around lung microvasculature and preventing pulmonary edema, especially in response to hypoxia, has recently been identified." (PMID 34681689, 2021).
reovirus infection (1 paper, 2025). "The distance between ANXA2 and the ER and ANXA2 and actin increased in infected cells relative to mock-infected cells, suggesting that the association of ANXA2 with both the ER and actin is altered during reovirus infection." (PMID 41283634, 2025). "Together, these data suggest that the disruption of the ER network and actin cytoskeleton that occurs during reovirus infection or in the absence of ANXA2 increases an association of actin with the ER." (PMID 41283634, 2025). "Together, these data demonstrate that the absence of ANXA2 and reovirus infection alters the actin cytoskeleton." (PMID 41283634, 2025). "Together, these data demonstrate that the actin cytoskeleton and ER network are remodeled during reovirus infection and are disrupted in the absence of ANXA2." (PMID 41283634, 2025). "In the absence of ANXA2, VF formation was accelerated in the early phases of reovirus infection, and yields of reovirus were increased." (PMID 41283634, 2025). "In the absence of ANXA2, the ER network is fragmented, similar to that observed during reovirus infection." (PMID 41283634, 2025). "Reovirus infection of cells lacking ANXA2 leads to accelerated VF formation and enhances the kinetics of reovirus replication." (PMID 41283634, 2025). "When ER membrane fragments are present prior to reovirus infection, as occurs in the absence of ANXA2, VFs are visible by immunofluorescence staining of nonstructural proteins as early as 7 h post-infection, which is approximately 2 h earlier than observed in cells expressing ANXA2." (PMID 41283634, 2025). "To confirm a function for ANXA2 in reovirus infection, we used CRISPR/Cas9 gene editing to engineer a new clonal HeLa cell line with a nonfunctional ANXA2 gene." (PMID 41283634, 2025).
retinal degeneration (1 paper, 2026). Degeneration of the retina. "Overall, it is possible that coordinated AnxA1/AnxA2 activity may mitigate retinal damage, improve the removal of toxic aggregates, and preserve vision, highlighting annexin pathways as promising therapeutic targets for retinal degeneration in PD and AD." (PMID 41639875, 2026).
retinal vein occlusion (1 paper, 2023). An occlusion of the retinal vein. "Proteins that were upregulated in our study and in experimental retinal vein occlusion included fibronectin, annexin A1, galectin-3, alpha-crystallin B chain, vimentin, annexin A2, STAT1, GFAP, osteopontin, vitronectin, and clusterin." (PMID 37175625, 2023).
rickettsia infection (1 paper, 2020). "In order to decipher the protein profile related to the CMHs observed in the ANXA2-KO mice post rickettsia infection, we performed a proteomic analysis of the whole brain protein lysate and isolated endosome." (PMID 32687500, 2020). "Interestingly, ANXA2-KO mice challenged by Ebola virus also exhibited CMHs and aberrant TJs whereas WT mice showed no signs of bleeding into CNS, indicating this pathology is not specific to rickettsia infection." (PMID 32687500, 2020). "The absence of ANXA2 may lead to a differential endosomal protein profile, which may shed light on the underlying mechanisms associated with the increased susceptibility of ANXA2-KO mice to CMH upon rickettsia infection." (PMID 32687500, 2020).
serous borderline ovarian tumors (1 paper, 2013). "Immunohistochemistry results showed positive immunostaining of annexin A2 in the epithelial cells of the normal surface epithelium, serous cystadenomas and serous borderline ovarian tumors." (PMID 23945256, 2013).
Splenomegaly (1 paper, 2016). Abnormal increased size of the spleen. "Furthermore, Annexin a2-deficient mice were more susceptible to A. phagocytophilum infection and showed splenomegaly, thrombocytopenia and monopenia." (PMID 27482714, 2016).
tuberous sclerosis (1 paper, 2023). Hereditary disease characterized by seizures, intellectual disability, developmental delay, and skin and ocular lesions. "ANXA2, an important annex in family member, was reported to be highly expressed in patients with tuberous sclerosis with seizures." (PMID 37302990, 2023).
Uterine leiomyoma (1 paper, 2019). The presence of a leiomyoma of the uterus. "This not only confirms the abnormal expression of ANXA2 in human AM tissues, but also indicates that the effect of ANXA2 in AM epitope and ectopic endometrium may be the same, and may be different from that in uterine leiomyoma." (PMID 31183557, 2019).
uveitis (1 paper, 2023). An inflammatory process affecting a part of or the entire uvea. "Mechanistically, ANXA2 aggravated the pathological process of uveitis via the ERK3/IL-17E pathway." (PMID 37828081, 2023).